MET (MET proto-oncogene, receptor tyrosine kinase)
Diseases named in the same sentence as MET in open-access papers (continued):
Sharing a sentence is not in itself a finding about the gene and the disease.
colorectal cancer (continued). "Intravenous administration of GE-137 in mice bearing HT29 tumors (human colorectal cancer with positive c-MET expression) resulted in specific accumulation of the probe in c-MET expressing tumors, whereas Cy5**-labeled scrambled peptide as a control group was only visible in the kidneys." (PMID 28485003, 2017). "Therefore, in the present study, we investigated the differential expression of RTKs c-MET, ErbB2, ErbB3, and down stream signaling molecules in primary samples of colorectal cancer patients, as well as in representative human colorectal cancer cell lines." (PMID 24205104, 2013). "All the cases examined could be classified as: ErbB3: c-MET co-over-expression colorectal cancer, ErbB3:ErbB2 co-over-expression colorectal cancer, and ErbB3:ErbB2: c-MET co-over-expression colorectal cancer." (PMID 24205104, 2013). "In addition, ectopic expression of miR-133b in colorectal cancer not only decreases MET expression, but also inhibits cell proliferation and induces apoptosis by G1-phase arrest in vitro and in vivo." (PMID 24391788, 2013). "The MEK and MET Inhibition in Colorectal Cancer trial (MErCuRIC1) was a phase I clinical trial aiming to test the combination of crizotinib with a MEK inhibitor, either binimetinib or PD-0325901, in CRC patients with either a KRAS mutation or aberrant c-MET activation." (PMID 37569406, 2023). "Furthermore, activated HGF might support the spread of metastatic colorectal cancer cells because they overexpress the HGF receptor MET." (PMID 36831450, 2023). "For example, SNHG4 was expressed highly in colorectal cancer, and promotes apoptosis of CD4+ T cells through a miRNA sponge binding to miR-144-3p and competing with the MET oncogene." (PMID 41154428, 2025). "In a study on colorectal cancer, EMI-137, a c-MET-targeted, fluorescently labeled tracer was evaluated." (PMID 40282528, 2025). "We also found that HSF4 regulated MET expression in RCC, consistent with a previous report describing this interaction in colorectal carcinoma." (PMID 40004241, 2025). "SOX13 is induced by hepatocyte growth factor through the JAK2/STAT3 signaling pathway, promoting metastasis in colorectal cancer by upregulating SNAI2 and c-MET expression." (PMID 39726600, 2024). "For example, in colorectal cancer cells, it has been shown that ICAM-1 can be phosphorylated on its intracellular domain by c-MET, which enables it to act as an adapter protein between c-MET and Src, promoting signaling." (PMID 37237555, 2023). "CNVs were determined across a set of 10 lung, breast, and colorectal cancer samples harboring a total of 11 known CNVs in the EGFR, MET, and ERBB2 genes as determined by orthogonal methods, including the OPA, OFA, and INFORM HER2 FISH assays." (PMID 37762091, 2023). "We found that, under the regulation of the MACC1/HGF/c-MET axis, the proliferation and metastasis of colorectal cancer are increased by MACC1, which can be a novel biomarker for predicting ICIs response in colorectal cancer." (PMID 35874635, 2022). "Studies have found that SOX13 can promote colorectal cancer metastasis by activating SNAI2 and c-MET." (PMID 34122521, 2021). "MET, NTRK1, and PPARG showed outlier expression in samples from three patients with GEJ adenocarcinoma, colorectal cancer, and urothelial cancer, respectively." (PMID 34385467, 2021). "CC-CAFs-CM resulted in increased phosphorylation of MET, AKT and expression of CD44 in colorectal cancer cells." (PMID 31367190, 2019). "The overexpression of FOXC2 also can induce MET expression and stimulate the hepatocyte growth factor (HGF)-MET signaling pathway, hence inducing the metastasis and invasion of colorectal cancer cells." (PMID 30360388, 2018). "In HT-29 and HTC-116 colorectal cancer cells, miR-1 acts as a tumor suppressor, reducing proliferation and migration by targeting the c-MET oncogene (Hepatocyte growth factor receptor), a member of the MAPK pathway." (PMID 29899866, 2018).
colorectal cancer (continued). "In summary, the novel fluorescent tracer based on c-MET-targeted peptide (GE-137) has successfully visualized expression of c-MET in preclinical study and was further used to detect colorectal carcinoma overexpressing c-MET in clinical setting." (PMID 28485003, 2017). "c-MET and its ligand HGF are frequently overexpressed in colorectal cancer (CRC) and increased c-MET levels are found in CRC liver metastases." (PMID 27793046, 2016). "It was reported recently that amplification of MET, FGFR1 and ERBB2 was involved in EGFR therapeutic resistance in colorectal cancer." (PMID 27738318, 2016). "MiR-340 is also identified to be a tumor suppresser in colorectal cancer through inhibiting growth and metastasis by targeting PTB1 and c-MET." (PMID 25831237, 2015). "HGF neutralizing antibody effectively reduces the activation of HGF/c-MET signaling, which blocks its ability to promote CPT-11 resistance in colorectal cancer cells." (PMID 26090722, 2015). "Taken together, our results show that colorectal cancer exhibits variation in oncogenic RTK due to different molecular patterns of expression including ErbB2/ErbB3/AKT and ErbB3/c-MET/MAPK." (PMID 24205104, 2013). "Metastasis-associated in colon cancer-1 (MACC1) has been newly identified to express highly in colorectal cancer (CRC) and promote tumor metastasis through transactivating metastasis-inducing HGF/MET signaling pathway." (PMID 22533346, 2012). "Furthermore, both c-MET and EGFR expressions show significant correlation with copy number alterations in colorectal cancer." (PMID 34512327, 2021). "Consistently, miR-34a could negatively regulate invasion and migration of CRC cells via repressing c-MET and long intergenic noncoding RNA (GAPLINC) suppresses the function of miR-34a in colorectal cancer." (PMID 30360560, 2018). "Among the up-regulated genes in colorectal cancer, we found 14 genes involved in signal transduction (TDGF1 and ENC1), transcription (SOX9, MYC, and HGFR/MET), nuclear transport (NUP62, NUPL1, NUP155, KPNA2, RANBP5, CSE1L/CAS, NTF2, and RANBP1) and cellular transport (SLCO4A1)." (PMID 16919171, 2006). "In colorectal cancer, the specific collaboration of MET with CD44 suggests that targeting the MET-CD44v interaction could be a promising therapeutic strategy to mitigate the tumorigenic effects of MET signaling." (PMID 39769452, 2024). "In order to investigate further the mechanism of downstream signaling of both molecular patterns in colorectal cancer, cell lysates were utilized to analyze the activation of AKT and MAPK signaling which are well-known downstream signaling pathways of ErbB2/ErbB3 and ErbB3/c-MET complexes." (PMID 24205104, 2013). "In order to identify suitable human colorectal cancer cell lines corresponding to the three molecular patterns which we discovered in the human samples, the expression of ErbB2, ErbB3 and c-MET in 9 human colorectal cancer cell lines was analyzed by western blotting (data not shown)." (PMID 24205104, 2013). "We propose that upregulation of MET could lead to transformation of colon epithelial cells and can initiate and enhance tumour growth in colorectal cancer irrespective of Wnt signalling." (PMID 15785735, 2005). "Similarly, in colorectal cancer, in depth computational analysis has shown the involvement of CREB5 in the metastatic signal network, suggesting that it promotes metastasis and invasiveness by boosting MET expression and activating the HGF-MET signaling pathway." (PMID 38418476, 2024). "In addition to EGFR, several important glycoproteins, such as MET, insulin-like growth factor-2 receptors (IGF-2R), and vascular endothelial growth factor receptor 2 (VEGFR2), also contain N-glycans and play critical roles in the pathogenesis of colorectal cancer." (PMID 25003232, 2014). "In the specific context of colorectal cancer, we observed reduced phosphorylation of EGFR and MET following lovastatin treatment, but no significant changes in SRC phosphorylation." (PMID 40832614, 2025).
colorectal cancer (continued). "For head and neck, stomach, and colorectal cancer cases, co-high expression of E2F1 and MET did not significantly impact survival." (PMID 38957115, 2024).
pancreatic cancer (181 papers, 2001 to 2026). "Specifically, high c-MET expression in pancreatic cancer ductal cells was associated with poor prognosis, underscoring its significance in tumor progression." (PMID 39592929, 2024). "Using the FindAllMarkers function, we identified distinct marker genes for pancreatic cancer ductal cells, revealing that c-MET was the only remaining gene after intersecting with pancreatic cancer-associated genes from GeneCards." (PMID 39592929, 2024). "Activation of the MET‐HGF signalling pathway has also been implicated in enhancing pancreatic cancer cell migration and invasion, facilitating cancer cells' ability to invade nerves." (PMID 38445456, 2024). "Previous studies have shown that MET was significantly associated with the prognosis of immune “hot” and “cold” pancreatic cancer and the combined application of MET inhibition and PD-L1 blockade showed a significant therapeutic efficacy." (PMID 36142142, 2022). "All these genes are upregulated in pancreatic cancer, and seven of them are significantly associated with unfavorable prognosis (MET, YAP1, PTPN14, EPS8, AHNAK, RALB, and AFAP1)." (PMID 34957301, 2021). "To determine the association of MET with PD-L1 in pancreatic cancer, we first investigated the influence of MET deficiency on PD-L1 expression." (PMID 34479614, 2021). "The aberrantly high levels and activation of MET are closely related with cancer onset, progression and metastasis and its upregulated in pancreatic cancer associated with grade." (PMID 33648511, 2021). "In pancreatic cancer, increased transcription leads to overexpression of c-MET, which is one of the most common causes of constitutive c-MET activation, and this increased c-MET promotes tumour occurrence and development through multiple mechanisms." (PMID 33816276, 2021). "Compared to the normal tissues, MET protein displays on average a sevenfold increase of expression in pancreatic tumor lesions; this feature has been recently linked to the activity of DYRK1A, a kinase involved in the regulation of the MET turn-over." (PMID 30544501, 2018). "It is well known that c-MET is deregulated in many human cancers including pancreatic cancer and can be activated by genetic mutations, gene amplifications, protein overexpression, or a ligand-dependent autocrine/paracrine signaling loop." (PMID 26404380, 2015). "Various forms of CEA, integrins, BRCA1, and tumor-associated glycoprotein-17 (TAG-17) are overexpressed on pancreatic tumor cells while c-MET, EpCAM, and CXCR-4 are also used as pancreatic cancer stem cell markers." (PMID 25157372, 2014). "However, recent research has identified MET as a pancreatic cancer‐specific RTK that is significantly associated with prognosis in both immunologically “hot” and “cold” pancreatic cancers." (PMID 38077251, 2023). "Interestingly, we showed that MET deficiency resulted in reduced protein stability of PD-L1, thereby lowering PD-L1 expression in pancreatic cancer cells." (PMID 34479614, 2021). "MET deficiency was found to facilitate lymphocyte infiltration into pancreatic tumors." (PMID 34479614, 2021). "This suggests that EGFR and MET are associated with the immune response in pancreatic cancer." (PMID 34479614, 2021). "In addition, IHC staining showed that elevated RON expression in the pancreatic cancer tissue samples was associated with distant metastasis, but that MET expression was associated with tumor size in our study." (PMID 31867280, 2019). "In summary, our findings demonstrate that Neuropathiazol inhibits pancreatic cancer progression via the MET-NeuroD1-Neurog3 axis." (PMID 41225636, 2025). "In PDAC patients, pancreatic stellate cells (PSCs) produce hepatocyte growth factor (HGF) and pancreatic cancer cells express MET." (PMID 39000029, 2024). "Initial examinations revealed heightened c-MET expression at the plasma membrane of pancreatic cancer cells, prompting in vitro assessment of TR1801-ADC in these cell lines." (PMID 39664377, 2024).
pancreatic cancer (continued). "This revelation prompted an investigation into circulating pancreatic stellate cells and the role of anti-c-MET adjuvant therapy in a newly developed mouse model following pancreatic tumor resection." (PMID 39664377, 2024). "As a result, SHR-A1403 demonstrated strong preclinical anti-tumor efficacy in pancreatic cancer, indicating its potential use as a c-MET-targeted antibody-drug conjugate treatment for PDAC in clinical practice." (PMID 39664377, 2024). "On the other hand, pancreatic cancer (PC), characterized by its aggressive nature and poor prognosis, has also been a focus of c-MET pathway research." (PMID 39664377, 2024). "A study of the human pancreatic cancer cell lines SW1990 and PANC-1 suggested that the binding of HGF and MET causes EMT-associated chemoresistance through its downstream PI3K/Akt pathway." (PMID 39000029, 2024). "The study revealed that HGF/c-MET dual inhibition curtailed angiogenesis and reduced the number of circulating pancreatic tumor cells." (PMID 39664377, 2024). "This review offers an in-depth exploration of the HGF/c-MET signaling pathway, trametinib’s mechanism, clinical applications, combination strategies, and future directions in the context of pancreatic cancer." (PMID 38473413, 2024). "High expression of EPYC, ANKRD22, ARNTL2, DSG3, KRT7, PRSS3 and MET predict poor prognosis of pancreatic cancer patients." (PMID 38184732, 2024). "HGF is produced by pancreatic stellate cells, and its receptor, c-MET, is expressed in pancreatic cancer cells and endothelial cells." (PMID 38473413, 2024). "It has been shown that serum HGF expression is higher in patients with invasive pancreatic cancer, and overexpression of MET is related to more severe invasion into lymph nodes as well as shorter survival, higher recurrence rates, and later stages of tumors." (PMID 39000029, 2024). "The critical role of the HGF/c-MET pathway in terms of its mitogenic and motogenic effects on cancer cells has been reported in several cancers, including pancreatic cancer." (PMID 38473413, 2024). "The result of human protein atlas (HPA) database showed the expression of TRAF1 and TYK2 were low in pancreatic cancer, the expression of MET was high." (PMID 38363947, 2024). "After intersecting these genes with previously identified transcriptomic differentially expressed genes and pancreatic cancer-related genes obtained from GeneCards, only the c-MET gene remained." (PMID 39592929, 2024). "Other features of the microenvironment in pancreatic cancer with the HGF/c-MET pathway include hypoxia, angiogenesis, metastasis, and the urokinase plasminogen activator positive feed-forward loop." (PMID 38473413, 2024). "Impressively, It has been demonstrated that c-MET is highly expressed and located at the plasma membrane of pancreatic cancer cells." (PMID 39664377, 2024). "For example, CD133+ cancer stem cells show high resistance to standard chemotherapy; CD44 sustains GEM resistance in pancreatic cancer cells; c-MET is also enhanced in GEM resistant (GR) pancreatic cancer cells and necessary for chemoresistance." (PMID 37327088, 2023). "Both chemical and antibody-based strategies have been evaluated to target cell surface markers, and some phase I clinical trials have proceeded for CD44 and c-MET in pancreatic cancer." (PMID 37327088, 2023). "We previously demonstrated that concomitant targeting of HGF and MET allows optimal blockage of the ligand/receptor axis, strongly reducing the metastatic spreading of pancreatic cancer cells." (PMID 37345079, 2023). "In pancreatic cancer, MET serves as both a marker and therapeutic target for CSCs,147 Additionally, the interaction between HGF/MET and tumor‐stromal cells helps to maintain the preferred glucose metabolism of pancreatic tumor stem cells." (PMID 38077251, 2023). "Taken together, our study found that G-6 is a potential anti-pancreatic cancer agent with regulation of MET/PTEN/TGF-β pathway." (PMID 36364317, 2022).